ACE (angiotensin I converting enzyme)
Diseases named in the same sentence as ACE in open-access papers (continued):
Sharing a sentence is not in itself a finding about the gene and the disease.
Hypertension (continued). "Patients carrying the A(−816)C SNP showed enhanced anti-hypertension response to the angiotensin-converting enzyme (ACE) inhibitor imidapril, which is converted to its active metabolite, imidaprilat, by CES1." (PMID 28677105, 2018). "Angiotensin-I converting enzyme inhibitors are widely used in the treatment of hypertension by inhibiting the ACE, responsible for the conversion of angiotensin I to the strong vasoconstrictor octapeptide angiotensin II." (PMID 30453595, 2018). "The ACE is an important gene of the RAAS that has been evaluated in the pathogenesis of hypertension, CAD, heart failure and, recently, longevity." (PMID 30159092, 2018). "We believe that the use of ACE inhibitors was found to be significant because of its frequent use regarding the treatment of arterial hypertension." (PMID 30089461, 2018). "Hereby, we explore the interaction of ACE and AGT gene polymorphisms with known risk factors such as hypertension for the development of DR in Chinese T1DM patients." (PMID 29484134, 2018). "Inhibition of the angiotensin-converting enzyme (ACE) is one of the main therapeutic targets in controlling hypertension." (PMID 30189590, 2018). "Captopril, an angiotensin-converting enzyme (ACE) inhibitor, has been widely used for therapy of arterial hypertension and cardiovascular diseases." (PMID 30183974, 2018). "Captopril is a sulfhydryl ACE inhibitor initially used in the treatment of hypertension and heart failure." (PMID 30126320, 2018). "Consistently, we found that ACE methylation was lower in the hypertension group than in controls, whereas HSD3B2 methylation was higher in subjects with EH independent of HCMV infection." (PMID 29752343, 2018). "Losartan increases bradykinin levels approximately 2-fold in arterial blood of patients with hypertension, similar to the increase seen with ACE inhibition." (PMID 30283782, 2018). "Inhibition of angiotensin-II’s formation by ACE-inhibitors has proved to be successful in the treatment of hypertension and related target organ damage." (PMID 30262795, 2018). "Unfortunately, a very low percentage (36.4%) of doctors (n = 9) in the present study selected ACE inhibitors as drug of choice in hypertension accompanied by renal disease." (PMID 29721335, 2018). "Angiotensin-converting enzyme (ACE) inhibitors are pharmaceutical drugs used primarily for the treatment of hypertension and congestive heart failure." (PMID 30183974, 2018). "One therapeutic approach to treating hypertension is inhibition of angiotensin I-converting enzyme (ACE) using synthetic drugs." (PMID 30275420, 2018). "Other randomized studies with a comparator have investigated the effect of treatment with ACE inhibitor on coronary microvascular function using positron emission tomography (PET) in patients with hypertension." (PMID 29883497, 2018). "In the treatment of hypertension in patients with metabolic syndrome and/or diabetes mellitus, ACE inhibitors (or sartans) and calcium channel blockers are preferred for well-known nephroprotective, angioprotective, and metabolic effects." (PMID 29805801, 2018). "The angiotensin-I converting enzyme (ACE) increases blood pressure and causes hypertension in inclined individuals." (PMID 30235793, 2018). "The aim of this study was to identify and characterize the bioactive compounds of Coriandrum sativum responsible for the treatment of hypertension and to explore their mechanism of action as angiotensin-converting enzyme (ACE) inhibitors." (PMID 30581531, 2018). "Angiotensin I-converting enzyme (ACE) peptides are bioactive peptides that have important value in terms of research and application in the prevention and treatment of hypertension." (PMID 30262795, 2018). "Pharmacological inhibitors targeting the RAS cascade, in particular renin inhibitors, ACE inhibitors and angiotensin receptor antagonists, have proved to be highly effective for the treatment of hypertension." (PMID 30518571, 2018).
Hypertension (continued). "Prescription drugs such as captopril, ramipril, lisinopril, and enalaprilare are synthetic ACE inhibitors, which have been widely used in the treatment of hypertension." (PMID 30189590, 2018). "Inhibition of ACE gene activity stops the production of angiotensin II in the body and is used as a therapeutic to treat high blood pressure." (PMID 30226856, 2018). "The effects found comparable to captopril, an ACE inhibitor and suggest that AA has potential in alleviating hypertension." (PMID 30233358, 2018). "The outcomes were the effects of preoperative hypertension, preoperative calcium antagonists regimen, preoperative ACE inhibitors regimen, and preoperative beta blocking agents regimen with POAF." (PMID 28286753, 2017). "An increased risk of hypertension has been associated with angiotensinogen (AGT), angiotensin-converting enzyme (ACE), and angiotensin II receptor 1 (AGTR1)." (PMID 28903744, 2017). "Angiotensin Receptor Blockers (ARBs) and Angiotensin-Converting Enzyme (ACE) Inhibitors (ACEIs) are now used successfully in the treatment of hypertension and other cardiovascular diseases." (PMID 28416734, 2017). "Inhibition of ACE by decreasing angiotensin II formation and increasing bradykinin production is necessary to control elevated blood pressure or hypertension." (PMID 28362352, 2017). "Among the processes related to hypertension, Angiotensin-I-Converting Enzyme (ACE) plays an important role in the regulation of blood pressure." (PMID 28761878, 2017). "In a clinical report, non-small cell lung cancer (NSCLC) patients taking ACE inhibitors to treat hypertension had better outcome after radiotherapy." (PMID 28209920, 2017). "Further, the results indicated that microginins inhibit ACE in a similar mechanism to that described for captopril, suggesting they are potential candidates for the control of arterial hypertension." (PMID 29206156, 2017). "It has been shown that the intake of beta blockers, ACE inhibitors, and angiotensin-1-receptor-antagonists reduces the measured augmentation index in patients with stages I and II arterial hypertension as well as in a variety of other indications." (PMID 27401737, 2017). "Hypertension is a serious threat to human health and food-derived ACE inhibitory peptides can regulate high blood pressure without side effects." (PMID 29160816, 2017). "Thiazide diuretics and ACE inhibitors were the most frequently used as a single drug, and ACE inhibitors were the BP lowering medications more frequently prescribed, but the rate of hypertension control is insufficient." (PMID 28751987, 2017). "Six categories of drugs (diuretics, calcium channel blockers, angiotensin II receptor blockers, ACE inhibitors, α-adrenergic antagonist, and β-blockers) are employed for anti-hypertension." (PMID 29160816, 2017). "Combination therapies based on ACE inhibitors with beta-blockers, diuretics or calcium-channel blockers represented the preferred options for treating patients with hypertension and TIA by GPs." (PMID 28515958, 2017). "For example, treatment of hypertension during pregnancy should avoid the potentially teratogenic ACE inhibitors and A2 receptor blockers." (PMID 29258594, 2017). "Drug therapy includes statins, angiotensin-converting enzyme (ACE) inhibitors, angiotensin II receptor blockers (ARBs), and metformin to target dyslipoproteinemia, hypertension, and dysglycaemia, respectively." (PMID 29234438, 2017). "Renin and ACE activity are used as biomarkers for disease states such as hypertension, diabetes, heart failure and renal diseases." (PMID 28423630, 2017). "ACE inhibitors primarily used for the treatment of heart failure and hypertension, were more commonly used in Italian men." (PMID 28870183, 2017). "For reasons of efficacy and cost, calcium channel blockers and thiazide-type diuretics are chosen as first-line treatments for hypertension, but ACE inhibitors are increasingly being used." (PMID 27965461, 2017).
Hypertension (continued). "Clinical studies have suggested that pharmacological inhibition on RAS is a critical component in the treatment of hypertension, in which the ACE inhibitors and Angiotensin 2 receptor blockers are the effective and most commonly used agents." (PMID 28293268, 2017). "Treating hypertension with synthetic drugs with angiotensin-I converting enzyme (ACE) inhibitory activity can have undesirable side effects, so food-derived peptides with ACE inhibitory activity are considered to be a better alternative." (PMID 29181389, 2017). "The use of Angiotensin Receptor Blockers (ARBs) and Angiotensin-Converting Enzyme (ACE) Inhibitors (ACEIs) to manage hypertension in cancer patients is correlated with improved survival outcomes for renal, prostate, breast and small cell lung cancer." (PMID 28416734, 2017). "Therapeutic concerns focus on the early introduction of ACE-blockers to diminish proteinuria and possible hypertension." (PMID 28057010, 2017). "Commonly-used drugs for hypertension are angiotensin-converting enzyme (ACE) inhibitors (including Enalapril) and angiotensin-receptor blockers (ARBs) (including Azilsartan, Telmisartan)." (PMID 29064399, 2017). "Approximately 90% of AS patients received concomitant therapy including beta-blockers (83%) and ACE inhibitors or angiotensin II receptor blockers for hypertension (36%)." (PMID 28246602, 2017). "Approximately 61% of SRC patients have good outcomes when hypertension is aggressively controlled with ACE inhibitors." (PMID 29051891, 2017). "Thiazide diuretics and ACE inhibitors were the most used BP lowering medications as single drugs, but the control rate of hypertension is insufficient." (PMID 28751987, 2017). "It is known that angiotensin I-converting enzyme (ACE) (EC 3.4.15.1) is a hypertension-responsible glycoprotein present both in biological fluids and in many tissues." (PMID 29279842, 2017). "Enalapril is an angiotensin-converting enzyme (ACE) inhibitor used in the treatment of hypertension, symptomatic heart failure and asymptomatic left ventricular dysfunction." (PMID 29017595, 2017). "Increased odds for hypertension in the boys’ population were higher with ACE ID + DD than with ACE II genotypes." (PMID 28903744, 2017). "Hypertension and treatment with angiotensin-converting enzyme inhibitor (ACE inhibitor) were less frequent in liver transplant recipients." (PMID 28395663, 2017). "Using virtual screening, MG 770 presented with comparable interactions with ACE, having features in common with commercial inhibitors such as captopril and enalaprilate, which are frequently used in the treatment of hypertension in humans." (PMID 29206156, 2017). "We prefer Phenotype 1 = {hypertension, ACE inhibitors}, Phenotype 2 = {diabetes, insulin} to Phenotype 1 = {hypertension, ACE inhibitors, insulin}, Phenotype 2 = {diabetes}, because the former is more distinct and meaningful than the latter." (PMID 28442772, 2017). "For example, the angiotensin-converting enzyme (ACE) inhibitors act as antihypertensive drugs, reducing hypertension." (PMID 28604647, 2017). "Accordingly, serum peptidases, such as ACE, ACE2, NEP, APN, and APA, which are important elements of the RAS, were studied here because dysregulation of these enzymes has been associated with hypertension and cardiovascular risk." (PMID 28174624, 2017). "Angiotensin II receptor blockers (ARB) such as Valsartan, Telmisartan, Losartan and angiotensin-converting enzyme (ACE) inhibitors such as Captopril, Lisinopril, Enalapril, Ramipril are widely used to treat hypertension." (PMID 28548953, 2017). "One patient was treated with an ACE-inhibitor due to moderate hypertension that was controlled under treatment." (PMID 28789630, 2017). "ACE cleaves angiotensin I to produce angiotensin II, which is known as a powerful vasoconstrictor in hypertension." (PMID 29065451, 2017).
Hypertension (continued). "Due to the important roles of ACE in the regulation of blood pressure, the inhibition of this enzyme has been used to treat hypertension." (PMID 28333109, 2017). "MG 770 presented with comparable interactions with ACE, having features in common with commercial inhibitors such as captopril and enalaprilate, which are frequently used in the treatment of hypertension in humans." (PMID 29206156, 2017). "The beneficial effects of angiotensin-converting enzyme (ACE) inhibitors in the treatment of arterial hypertension, congestive heart failure, and other cardiovascular diseases are well documented." (PMID 28386233, 2017). "Angiotensin-I-converting enzyme (ACE) inhibitors like synthetic drugs are widely used to control hypertension." (PMID 28333109, 2017). "The IC50 values of the two saveloys were compared with Captopril, which is a known ACE inhibitor used in the medical treatment of hypertension." (PMID 27004118, 2016). "The main goal of the work was to produce an ACE inhibitor proteolysate derived from marine source with desirable functional characteristics comparable to synthetic drugs for amelioration of hypertension." (PMID 27706040, 2016). "There were fewer newly diagnosed patients in the AZL-M group (34.2 % vs. 43.9 %), and those with established hypertension had a longer mean time since diagnosis in comparison to the ACE-inhibitor group (67.2 ± 65.3 months vs. 57.7 ± 60.9 months; p < 0.001)." (PMID 26956148, 2016). "A key mechanism underpinning this hypertension is an overactivated renin angiotensin system because ACE inhibition reverses the hypertension induced by perinatal DDT exposure." (PMID 27325568, 2016). "The levels of MMPs depend on the presence of diabetic nephropathy, hypercholesterolemia, increased oxidative stress, ACE inhibitors, and hypertension." (PMID 27829825, 2016). "Patients with TCC were more likely to have hypertension and use medications (beta-adrenergic blocking agents, ACE inhibitors, antiplatelet medications, and lipid-lowering drugs) compared with healthy controls." (PMID 27401603, 2016). "Angiotensin Converting Enzyme (ACE) inhibitors is a drug class that is commonly used in treating hypertension." (PMID 27110504, 2016). "The amlodipine- losartan combination treatment reduced obesity, hypertension, hypertriglyceridemia and gene changes such as ACE, AT IA, eNOS and Tn I in our study." (PMID 27051525, 2016). "STNx led to hypertension, diastolic dysfunction, left ventricular hypertrophy, cardiac fibrosis, and increased cardiac ACE, ACE2, Ang II and Ang 1–7 levels." (PMID 27571511, 2016). "A study in Japan showed that 33% of patients with hypertension and diabetes were taking ACE inhibitors and/or ARBs." (PMID 27437997, 2016). "After 10 years, data about 7 patients were available: 5 of group A, 3 with systemic hypertension successfully controlled with ACE inhibitors, and 2 of group B, who had normal systolic pressure values." (PMID 26925287, 2016). "Baseline eGFR and the risk of CT-CIN showed a nonlinear relationship after adjustment for age, sex, BMI, history of diabetes mellitus, history of hypertension, serum albumin level, and the use of statins, ACE inhibitors, or ARBs." (PMID 27149474, 2016). "In the total study population, 75 % had diagnosed hypertension, 26 % were on treatment with ACE-inhibitors/Angiotensin receptor blockers, and 35 % were on treatment with beta-blockers." (PMID 27585990, 2016). "Since hypertension is becoming a serious health issue all over the world, lots of studies have been done about ACE inhibitory peptides, which are derived from food protein." (PMID 27706040, 2016).
Hypertension (continued). "Immunofluorescence revealed that renovascular hypertensive rats had a significant increase of ACE and AT1-R expression in the PVN compared with SHAM rats." (PMID 27881877, 2016). "Age, sex, history of diabetes mellitus or hypertension, use of ACE inhibitors or ARBs, hemoglobin level, and albumin level showed significant differences across the eGFR groups." (PMID 27149474, 2016). "On a positive note, our study provides evidence that ACE inhibition normalizes hypertension of mice perinatally exposed to DDT." (PMID 27325568, 2016). "Synthetic drugs targeting inhibition of ACE are normally used for the clinical treatment of hypertension such as captopril, enalapril, and alcacepril." (PMID 27271639, 2016). "For example, the oxazepin-4-one A is a strong inhibitor of angiotensin-converting enzyme (ACE) and found to play a prominent role in the current approaches to hypertension and diabetic nephropathy therapy, end-organ protection and heart failure treatment." (PMID 27271585, 2016). "According to our findings, the relationship of ACE gene I/D polymorphism with BMI-defined obesity is insignificant in Chinese patients with T2DM; the obese group obtained higher ratio of hypertension." (PMID 28115791, 2016). "White compared with black patients with hypertension are more likely to respond to β-blockers, ACE inhibitors, and ARBs, whereas for black patients, treatment with a diuretic or calcium channel blocker (CCB) is more likely to be effective." (PMID 27037223, 2016). "It has been well documented that angiotensin-converting enzyme (ACE) inhibitors are effective in the treatment of hypertension and chronic HF." (PMID 28032307, 2016). "Pre-treatment of mice with the ACE inhibitor perindopril abolished resistin-induced hypertension and IR, suggesting that the action of resistin is inhibited when the RAS is blocked." (PMID 26917360, 2016). "Our result is further confirmed by the fact that FIR-irradiated SHRs had significantly reduction of plasma ACE activity when compared to the untreated control, suggesting a role of elevated plasma ACE activity in modulating hypertension conditions." (PMID 26857237, 2016). "Lisinopril, a potent, competitive inhibitor of angiotensin-converting enzyme (ACE), is used to treat hypertension and symptomatic congestive heart failure." (PMID 27196054, 2016). "Angiotensin II and angiotensin converting enzyme (ACE) play an important role in the process of hypertension and atherosclerosis." (PMID 27231920, 2016). "Captopril, an ACE inhibitor, is currently used in the treatment of hypertension and was used as a positive control in this study." (PMID 26927038, 2016). "To date, there is a general consensus on angiotensin converting enzyme (ACE) inhibitors as first-line treatment for hypertension in diabetic subjects." (PMID 27007793, 2016). "The ultimate goal of this study was to investigate ACE inhibitory properties of proteolysate derived from marine source, which can be used as alternative therapy for prevention and treatment of hypertension." (PMID 27706040, 2016). "Adult mice were treated with an angiotensin converting enzyme (ACE) inhibitor, captopril, to evaluate sensitivity to amelioration of DDT-associated hypertension by ACE inhibition." (PMID 27325568, 2016). "Lisinopril is a drug of the angiotensin-converting enzyme (ACE) inhibitor class that is primarily used in the treatment of hypertension." (PMID 27222603, 2016). "It is highly recommended that the ACE-inhibitory peptides from razor clam hydrolysates be employed in the development of nutraceuticals and pharmaceuticals for the treatment of hypertension." (PMID 27271639, 2016). "Here we report that captopril, an angiotensin converting enzyme (ACE) inhibitor used to treat high blood pressure, extended mean lifespan." (PMID 26918946, 2016). "Captopril is an angiotensin-converting enzyme (ACE) inhibitor used to treat high blood pressure in humans." (PMID 26918946, 2016).